GCM2 (GCM transcription factor 2)
Description:
Transcription factor that binds specific sequences on gene promoters and activate their transcription. Through the regulation of gene transcription, may play a role in parathyroid gland development.
Synonyms: hGCMb; GCMB; FIH2; HRPT4
Tractability: No criterion of Open Targets' tractability assessment is met for any kind of drug.
Gene: Protein-coding gene on chromosome 6 (10,873,223 to 10,882,041, reverse strand). Ensembl gene ENSG00000124827.
Subcellular location: Nucleus
Gene Ontology:
Molecular function: DNA-binding transcription factor activity, RNA polymerase II-specific; protein binding; sequence-specific DNA binding; sequence-specific double-stranded DNA binding; DNA binding; RNA polymerase II cis-regulatory region sequence-specific DNA binding; DNA-binding transcription activator activity, RNA polymerase II-specific
Biological process: intracellular calcium ion homeostasis; intracellular phosphate ion homeostasis; parathyroid gland development; transcription by RNA polymerase II; gliogenesis; regulation of transcription by RNA polymerase II; positive regulation of transcription by RNA polymerase II; regulation of DNA-templated transcription
Cellular component: nucleus; chromatin
Genetic constraint (gnomAD): Loss-of-function variants: 18 observed, 22.14 expected, observed/expected ratio (o/e) 0.81, 90% interval 0.56 to 1.21. The upper end of that interval is the gene's LOEUF score, 1.21, which puts it in group 5 of 6, group 1 being the genes least tolerant of losing a copy. Missense variants: 521 observed, 658.07 expected, observed/expected ratio (o/e) 0.79, 90% interval 0.74 to 0.85. Synonymous variants: 222 observed, 241.38 expected, observed/expected ratio (o/e) 0.92, 90% interval 0.82 to 1.03.
Homologues: Orthologues: chimpanzee GCM2 (99% identical), macaque GCM2 (96% identical), dog GCM2 (81% identical), rabbit GCM2 (75% identical), pig GCM2 (74% identical), guinea pig GCM2 (72% identical), mouse Gcm2 (69% identical), rat Gcm2 (68% identical), tropical clawed frog gcm2 (51% identical), zebrafish gcm2 (48% identical), Drosophila melanogaster gcm (29% identical), Drosophila melanogaster gcm2 (29% identical). Paralogues in human: GCM1 (30% identical).
Diseases named in the same sentence as GCM2 in open-access papers:
GCM2 is named in the same sentence as 46 diseases in open-access papers, as found by Europe PMC text mining. Sharing a sentence is not in itself a finding about the gene and the disease. The quoted sentences say what the papers report.
hypoparathyroidism (22 papers, 2013 to 2025). Hypoparathyroidism is an endocrine disorder in which the parathyroid glands in the neck do not produce enough parathyroid hormone (PTH). "GCM2 plays a critical role in the development and maintenance of the parathyroid gland, and several pathogenic variants associated with isolated hypoparathyroidism have been identified." (PMID 40655406, 2025). "In contrast, seven heterozygous GCM2 variants associated with hypoparathyroidism have been reported to date." (PMID 40655406, 2025). "Herein, we present the case of a patient diagnosed with isolated hypoparathyroidism with a novel de novo heterozygous frameshift pathogenic variant of the GCM2 gene." (PMID 40655406, 2025). "Most cases of hypoparathyroidism caused by GCM2 pathogenic variants result from homozygous or compound heterozygous loss-of-function variants, with a limited number of heterozygous variants reported." (PMID 40655406, 2025). "Most cases of hypoparathyroidism caused by GCM2 pathogenic variants result from homozygous or compound heterozygous loss-of-function variants, with only a limited number of heterozygous variants reported." (PMID 40655406, 2025). "In summary, we report a case of isolated hypoparathyroidism in an adult woman, caused by a novel de novo heterozygous frameshift pathogenic variant of the GCM2 gene." (PMID 40655406, 2025). "Whole exome sequencing on our proband revealed a homozygous pathogenic variant in the GCM2 gene (Gln392*) consistent with a molecular diagnosis of familial isolated hypoparathyroidism." (PMID 39439810, 2024). "GCMb is important for parathyroid gland development, as evidenced by Gcm2 knockout mice developing hypoparathyroidism and LOF GCM2 mutations causing familial isolated hypoparathyroidism." (PMID 38038882, 2024). "It has been shown that gcm2-null mice develop parathyroid hypoplasia and hypoparathyroidism, and that homozygous and heterozygous germline inactivating GCM2 pathogenic variants in humans lead to hypoparathyroidism." (PMID 38130397, 2023). "In the present study, we examined GCM2 mutations in two families presenting with hypoparathyroidism." (PMID 35038313, 2022). "We provide evidence that two novel GCM2 R67C inactivating mutations with an inability to bind DNA are causative of hypoparathyroidism." (PMID 35038313, 2022). "GATA3 is upstream of Gcm2 and causes Gcm2 dysregulation; its haploinsufficiency causes the hypoparathyroidism, deafness, and renal anomaly syndrome, which results in these three pathologies." (PMID 32517664, 2020). "Pathogenic mutations in the parathyroid hormone gene (PTH) and glial cells missing transcription factor 2 (GCM2) have been associated with both autosomal dominant and recessive hypoparathyroidism." (PMID 32986719, 2020). "Glial cells missing (GCM2) gene mutation results in isolated hypoparathyroidism with early onset of hypoparathyroidism due to parathyroid gland agenesis." (PMID 30540559, 2019). "Summary of reports on heterozygous GCM2 variants associated with hypoparathyroidism." (PMID 40655406, 2025). "Additionally, conditional Gcm2 knockout in adult mice inhibited cell proliferation, increased cell death in the parathyroid glands, and caused hypoparathyroidism." (PMID 40655406, 2025). "This case provides further evidence that heterozygous GCM2 variants can lead to hypoparathyroidism." (PMID 40655406, 2025). "Although the patient had no family history of the disease or other features suggestive of genetic abnormalities, genetic testing revealed a novel de novo heterozygous frameshift pathogenic variant of GCM2 that contributed to the development of hypoparathyroidism." (PMID 40655406, 2025). "GCM2 is homologous to the Drosophila glial cells missing gene and encodes a transcription factor implicated in parathyroid gland development, and mutations in GCM2 have been reported in familial hypoparathyroidism." (PMID 24034811, 2013).
hypoparathyroidism (continued). "Glial cells missing transcription factor 2 (GCM2) is one of the genes responsible for isolated hypoparathyroidism." (PMID 40655406, 2025). "According to the American College of Medical Genetics and Genomics guidelines, this heterozygous GCM2 frameshift variant was classified as pathogenic (PVS1+PS2+PM2) and determined to be the cause of hypoparathyroidism in this patient." (PMID 40655406, 2025). "The GCM2 or GCMB gene encodes an important transcription factor for parathyroid adenomas, while familiar absence causes hypoparathyroidism." (PMID 37223014, 2023). "The mutation, a substitution of arginine for cysteine at position 67 in the DBD of the transcription factor GCM2 (R67C), segregated with hypoparathyroidism in the families." (PMID 35038313, 2022). "We provided novel insight into the structure−function relationships of the GCM2 mutant proteins that we identified in hypoparathyroidism, through several approaches." (PMID 35038313, 2022). "We characterized 2 families with hypoparathyroidism and 19 with FIHP in which we examined the mechanism of action of GCM2 variants." (PMID 35038313, 2022). "In our genetic study, two variants in the GCM2 gene were found in two patients with hypocalcemia (GS0198) and hypoparathyroidism (CA0117)." (PMID 33536578, 2021). "Similarities between familial isolated hypoparathyroidism in humans and the refractory hypocalcemia observed in Thoroughbred foals led to the hypothesis that genetic variants in PTH, GCM2, CASR, GNA11 or TRPM6 may be responsible for the disease in the horse." (PMID 32986719, 2020). "GCM2‐deficient mice failed to develop parathyroid and showed symptoms of hypoparathyroidism." (PMID 38494923, 2024). "The aim of this study was to analyze variants of the gene glial cells missing-2 (GCM2), encoding a parathyroid cell-specific transcription factor, in familial hypoparathyroidism and in familial isolated hyperparathyroidism (FIHP) without and with parathyroid carcinoma." (PMID 35038313, 2022). "The similar clinical presentation between familial isolated hypoparathyroidism in humans and equine idiopathic hypocalcemia led to the hypothesis that a coding variant within PTH, GCM2, CASR, GNA11 or TRPM6 would be associated with idiopathic hypocalcemia of TB foals." (PMID 32986719, 2020). "Although the variant in our patient was not evaluated using an in vitro assay, its high similarity to previously reported pathogenic variants strongly suggests that the variant protein exerts a dominant-negative effect, impairing GCM2 function and leading to hypoparathyroidism." (PMID 40655406, 2025). "Greater than 90% of AIRE mutation-negative probands with suspected familial hypoparathyroidism had apparently isolated hypoparathyroidism, and around 30% of these probands were found to have an abnormality affecting either the CASR, GATA3, GCM2, GNA11 genes or the 22q11.2 chromosomal region." (PMID 35521792, 2022).
parathyroid adenomas (9 papers, 2010 to 2025). "A GCM2 variant, p.V382M, was identified in 30 parathyroid adenomas and clustered in a small domain of 17 amino acids termed as the ‘C-terminal conserved inhibitory domain (CCID)’." (PMID 35038313, 2022). "GCM2 variants have also been found in 396 sporadic parathyroid adenomas with a frequency of activating GCM2 CCID (p.V382M and p.Y394S) and Y282D variants of 1.52 and 5.05%, respectively." (PMID 35038313, 2022). "Moreover, somatic GCM2 activating mutations have been also reported in 6.57% of sporadic parathyroid adenomas." (PMID 40329145, 2025). "Germline mutation in the GCM2 gene was found in patients with sporadic disease threefold more frequent compared to the control group, concluding that patients with this mutation have predisposition in parathyroid adenoma development." (PMID 37223014, 2023). "GCM2 has been reported to be downregulated, unchanged or upregulated in human parathyroid adenomas." (PMID 35038313, 2022). "Parathyroid adenomas have been found in the human thymus, and have been shown to express Gcm2, indicating that intrathymic adenomas could be the result of uncontrolled growth of the misplaced parathyroid cells." (PMID 21203493, 2010). "GCM2 is a parathyroid-specific transcription factor involved in parathyroid embryogenesis; during adult life, GCM2 maintains CASR expression, and downregulated GCM2 transcripts have been reported in parathyroid adenomas." (PMID 33670622, 2021).
Hypocalcemia (8 papers, 2017 to 2024). An abnormally decreased calcium concentration in the blood. "Although all 3 have the same GCM2 variant, they exhibit varying degrees of hypocalcemia and require different doses of treatment, reflecting the heterogeneity of this disease." (PMID 39439810, 2024). "In the present study, we report a novel variant of uncertain significance in the GCM2 gene in a family from Spain with severe hypocalcemia." (PMID 33536578, 2021). "Importantly, a novel variant in the GCM2 gene (p.(Ser487Phe)) has been found in a patient with hypocalcemia." (PMID 33536578, 2021). "This was consistent with previous findings in which the GCM2 expression level was significantly upregulated in PA and correlated with a decrease in the response to hypocalcemia." (PMID 34054720, 2021). "Interestingly, our data suggested that the decrease in PTG CaSR expression, which is important in the development of SHPT, was caused by the early decrease in PTG Gcm2 expression, followed by the effect of 1,25(OH)2D reduction, PTG VDR reduction, hypocalcemia and hyperphosphatemia." (PMID 32517664, 2020). "Only two patients with hypocalcemia (one of them is not included in the manuscript) had the p.Ala393_Gln395dup duplication in the GCM2 gene (2/26)." (PMID 33536578, 2021).
familial isolated hyperparathyroidism (5 papers, 2022 to 2024). A rare, autosomal dominant hereditary syndrome characterized by hypercalcemia, abnormally high levels of parathyroid hormone, and isolated hyperfunctioning parathyroid tumors. "Variants of GCM2, a parathyroid-specific embryonic transcription factor, increase the transactivation of the PTH promoter in vitro and are associated with familial isolated hyperparathyroidism (FIHP; OMIM#614373 HRPT4)." (PMID 39409111, 2024). "Non-syndromic hereditary hyperparathyroidism, called familial isolated hyperparathyroidism (FIHP), can be caused by the incomplete manifestation of mutations of syndrome-related genes such as MEN-1, CDC73, GCM2, CDKN1A, CDKN1B, or CDKN2C." (PMID 36900197, 2023). "Interestingly, we identified one GCM2 variant (c.1162A>G [p.Lys388Glu]) and five APC variants that were previously reported in familial isolated hyperparathyroidism, benign sporadic PHPT, and parathyroid cancer." (PMID 35586626, 2022).
hyperparathyroidism (5 papers, 2019 to 2025). Hyperfunction of the parathyroid glands resulting in the overproduction of parathyroid hormone. "Other variants are associated with hyperparathyroidism, with an overall higher frequency of GCM2 variants in sporadic and familial PHPT than in the general population." (PMID 38130397, 2023). "Western blot analysis of extracts from HEK293-transfected cells showed that all variants associated with hyperparathyroidism had the same level of expression as WT GCM2." (PMID 35038313, 2022). "GCM2 expression was reported to be upregulated in abnormal parathyroid glands of hyperparathyroidism, and GCM2-activating variants have been proposed as candidate predisposition alleles in sporadic parathyroid tumors." (PMID 35038313, 2022). "Future studies aimed at identifying co-operating factors that may help in transmitting the actions of GCM2 may therefore further delineate the potential role of variant GCM2 in causing parathyroid tumors and biochemical hyperparathyroidism." (PMID 35038313, 2022). "In conclusion, we have identified novel and recurrent heterozygous activating variants of the GCM2 gene and provided evidence that they are potential contributors to the pathogenesis of hyperparathyroidism and could be associated with parathyroid carcinoma." (PMID 35038313, 2022). "GCM2 encodes a transcription factor that is a critical regulator of the development of the parathyroid gland, and its activating germline variants are responsible for familial isolated hyperparathyroidism." (PMID 34054720, 2021). "Consequently, whether identification of germline GCM2 variants may sometimes contribute to a more malignant form of hyperparathyroidism requires further consideration." (PMID 35038313, 2022). "After the diagnosis of hyperparathyroidism was established in the sons and other known genetic PHPT forms were excluded (by hormonal and genetic analyses), screening of GCM2 confirmed the presence of the p.Y394S variant." (PMID 35038313, 2022). "In addition, it is known that abnormalities of Gcm2 occur in primary hypoparathyroidism, hyperparathyroidism, and parathyroid tumors with parathyroid cell proliferation." (PMID 30677043, 2019). "Our in vitro experiments indicate that GCM2 hyperactive variants display enhanced transactivation of the human PTH promoter compared to WT, which might possibly contribute to the development of hyperparathyroidism." (PMID 35038313, 2022).
primary hyperparathyroidism (5 papers, 2021 to 2025). "Features of patients with isolated primary hyperparathyroidism diagnosed with a GCM2 p.Y394S variant, CASR, and AP2S1 mutations." (PMID 38130397, 2023). "Mutation of the C-terminal conserved inhibitory domain of GCM2 can cause primary hyperparathyroidism." (PMID 33803633, 2021). "However, we also found variants in genes associated with primary hyperparathyroidism (GCM2), renal hypophosphatemia with or without rickets (SLC34A1, SLC34A3, SLC9A3R1, VDR, and CYP27B1), DiGeorge syndrome (TBX1 and NEBL), and hypophosphatasia (ALPL)." (PMID 38586466, 2024).
Hypercalcemia (4 papers, 2022 to 2025). An abnormally increased calcium concentration in the blood. "The phenotype of our patients with the GCM2 p.Tyr394Ser variant presented with asymptomatic mild to moderate hypercalcemia, and are low urinary calcium excretion fraction was below 1% or below 2% and may thus overlap with the phenotype observed in FHH." (PMID 38130397, 2023). "A review of the clinical, laboratory, imaging, and pathologic findings in our patients with the GCM2 p.Tyr394Ser variant showed that all patients had asymptomatic disease and mild (patients 1 and 3) or moderate (patient 2) hypercalcemia, with mild to moderate elevated PTH." (PMID 38130397, 2023). "Earlier published series described GCM2-related pHPT as a severe variant with very high calcemia and PTH levels series; however, more recent series have found a prevalence of mild hypercalcemia, even with low urinary calcium excretion fraction." (PMID 40329145, 2025). "Whether GCM2 variant-induced increased PTH mRNA expression, if present, could then cause increased PTH secretion and potentially contribute to hypercalcemia is possible but remains an area for future studies." (PMID 35038313, 2022).
parathyroid tumors (4 papers, 2019 to 2025). "Activating germline variants in GCM2 that map to the CCID domain have also been found in low frequency among patients with typically-presenting sporadic HPT who underwent parathyroid tumor excision and appear to be of low penetrance." (PMID 33716975, 2021). "However, the higher rate of malignant and atypical parathyroid tumors in GCM2 mutation carriers is based on very few cases; thus, further studies and surveillance of GCM2 mutation carriers’ kindred are needed to confirm this association." (PMID 40329145, 2025).